CD69 (CD69 molecule)
Diseases named in the same sentence as CD69 in open-access papers (continued):
Sharing a sentence is not in itself a finding about the gene and the disease.
Sepsis (continued). "By 72h, both water and alcohol fed animals demonstrate increased CD69 expression in sepsis compared with sham laparotomy." (PMID 27861506, 2016). "It has recently been shown that in the early phase of human severe sepsis there is an increase in the percentage of activated (CD69+) T-cell subsets compared to healthy controls." (PMID 24465843, 2014). "Previous reports showed that the upregulation of CD69 is a sensitive marker in neonatal sepsis and reported the presence of circulating CD56+CD69+ NK cells in sepsis." (PMID 23098236, 2012). "While CD69 was barely expressed on NK cells of healthy volunteers, it was increased and detected in sepsis and SIRS patients." (PMID 23098236, 2012). "Other cell surface markers like CD40 and CD69 whose expression increases in severe sepsis and decreases with the resolution of sepsis were significantly up- regulated at early time points, and decreased at 18 h (data not shown)." (PMID 23009705, 2012). "While there was no significant modification of CX3CR1 and CD16 expression, we found a trend for an enhanced expression of the early activation marker CD69 in vivo after sepsis." (PMID 23098236, 2012). "Our data raises the prospect that CD69+ naïve CD4 T cells may be a useful biomarker in the diagnosis of sepsis." (PMID 41208955, 2025). "If this is the case in the human system also, it may indicate that CD69 drives a more inflammatory phenotype and a possible pathological response of this cell population in sepsis." (PMID 41208955, 2025). "Additionally, septic patients with G- sepsis had a noticeably lower ratio of CD3+CD4+CD69+T/CD3+CD8+CD69+T than that in the G+ sepsis subgroup." (PMID 36703970, 2022). "To further identify the impact of T regs expansion on the activities of lymphocytes in the late phase of sepsis, we compared the percentage of CD69+ cells and IFN-γ-producing cells in T cells and NK cells in either T regs-depleted LPS mice or isotype control Abs-treated LPS mice." (PMID 26918357, 2016). "In the CD44hi subset at 24h, sepsis increased CD69 in the water-fed group." (PMID 27861506, 2016). "Interestingly, the T cells show an elevated activation state after sepsis by the activation marker CD69 16 and now here by the activation marker CD25." (PMID 26734459, 2015). "While the bulk of the findings presented above argued for the absence of fundamental defects in T-cell function in post-acute sepsis, some observations like the lower CD69 and CD25 response to in vivo antigen challenge argued for subtle changes in the response of T-cells to antigen." (PMID 25541945, 2014). "CD69 was highly expressed in the sepsis‐associated C1 cluster but not in C10." (PMID 40041474, 2025). "Furthermore, while the expansion of CD69+ naïve CD4+ T cells in sepsis is interesting, it may reflect cohort-specific factors and requires validation in larger, independent cohorts." (PMID 41208955, 2025). "Furthermore, CD3+CD8+CD69+T could be a target of immunomodulation intervention in G- sepsis, and the adjustment of immunological status could be one of the most valuable approaches to improve the prognosis." (PMID 36703970, 2022). "The prognostic role of low level CD3+CD4+CD69+T/CD3+CD8+CD69+T ratio in G- sepsis may be similar to that of low level CD4+T/CD8+T ratio in sepsis in previous studies, which may reflect the imbalance of T suppression/activation of adaptive immune response during pathophysiologic process in sepsis." (PMID 36703970, 2022). "In addition, the percentage of CD69+ cells was higher among NK cells of sepsis patients." (PMID 23098236, 2012). "Correlation analyses of MAIT cell activation markers and soluble factors in sepsis patients revealed positive, albeit weak, correlations between the MAIT cell CD69 expression and the levels of IL‐12 and IL‐15 and with IFNγ and TNF in the plasma." (PMID 40041474, 2025).
Sepsis (continued). "Sepsis patients tended to have a slightly higher frequency of CD38+, CD69+ and lymphocyte activation gene 3 (LAG‐3)+ MAIT cells compared with non‐sepsis patients, although not significantly so." (PMID 40041474, 2025). "We show increased proportions of this CD69+ naïve CD4+ T cell population, increased effector CD4+ T cells and yet decreased T cell activation in sepsis." (PMID 41208955, 2025). "B cell phenotypes change in sepsis, with a marked reduction of CD19+CD23+ activated regulatory B cells and CD19+CD5+ natural responder B1a cells, although the number of CD19+CD69+ early activated B cells remains unaffected." (PMID 38474403, 2024). "The initial phase of sepsis is characterized by an increased number of activated NK cells expressing high levels of TLR-2/4/9 and CD69, as well as high plasma concentration of granzyme A, interferon (IFN)-γ, and IL-12p40." (PMID 38474403, 2024). "In G- sepsis (versus G+ sepsis), we observed that both CD3+CD69+T and CD3+CD8+CD69+T (%) were remarkably upregulated, while CD4+T/CD8+T ratio, CD3+CD4+CD69+T (%) and CD3+CD4+T were downregulated (although the latter two indexes without significant difference)." (PMID 36703970, 2022). "In summary, it was found that compared with patients with G+ sepsis, patients with G- sepsis exhibited a higher percentage of CD3+CD8+CD69+T cells and a noticeably lower CD3+CD4+CD69+T/CD3+CD8+CD69+T ratio." (PMID 36703970, 2022). "We compared the mean fluorescence intensity (MFI) of CD69 and CD28 expression on gated CD4+ T and CD8+ T cells in the two sepsis models." (PMID 33717146, 2021). "Separately, it was reported that the expression levels of positive activated molecule NK62D, TLR-2/4/9, and CD69 on NK cells and plasma IFN-γ in sepsis patients were significantly higher than those in healthy controls." (PMID 33076951, 2020). "In neither group was there a difference between water sepsis and alcohol sepsis in frequency of CD69 positivity, however, this dynamic change in the kinetics of expression suggests that alcohol delays the process of CD4+ T cell activation in sepsis." (PMID 27861506, 2016). "Splenocytes from T reg-depleted sepsis mice (given 100 μg anti-CD25 mAb) contained higher percentages of CD4+CD69+, CD8+CD69+ activated T cells and CD3−NK1.1+ CD69+ activated NK cells compared with isotype matched controls." (PMID 26918357, 2016). "We demonstrated a defect of NK cells for both CD69 upregulation and IFN-γ production ex vivo in response to accessory cytokines and PAMPs, or accessory cytokines and whole bacteria in sepsis and SIRS patients." (PMID 23098236, 2012). "Consequently, we have reported a population of CD69 expressing naïve CD4+ T cells for the first time in sepsis, which advances our understanding of sepsis pathophysiology." (PMID 41208955, 2025). "While the expression of CD69 was upregulated during sepsis, the increased CD69+ naïve CD4+ T cell population has not been reported previously in this condition." (PMID 41208955, 2025). "Measure the expression of CD64 and CD69 on lymphocytes in clinical and confirmed sepsis patients and compared to that in infants without sepsis." (PMID 39978117, 2025). "Expression of CD64 on neutrophils and CD69 on NK cells did not increase in the clinical or confirmed sepsis groups compared to the without sepsis group." (PMID 39978117, 2025). "In the present study, we illustrated a novel discrimination model of the low ratio of CD3+CD4+CD69+T/CD3+ CD8+CD69+T, PCT>0.53 ng/ml, and CO2CP<26.5 mmol/L, which could strongly predict the diagnosis of the G- sepsis (versus G+ sepsis), with an AUC of 0.947." (PMID 36703970, 2022). "Moreover, the integrated profile of the lower CD3+CD4+CD69+T/CD3+CD8+CD69+T ratio, PCT>0.53 ng/ml, and CO2CP<26.5 mmol/l was favored to the differentiation of G- sepsis from G+ sepsis, with an AUC of 0.947 in the regression model." (PMID 36703970, 2022).
Sepsis (continued). "Our finding revealed that the percentage of CD3+CD69+ T and CD3+CD8+CD69+ T subset were higher in the bacterial sepsis group (versus the no infection group), and an even higher in the G- sepsis subgroup than that in the G+ sepsis subgroup." (PMID 36703970, 2022). "The expression of early activation marker CD69 increased significantly at 12 h and then declined slowly on both CD4+ and CD8+ T cell subsets in AS mice, suggesting that both CD4+ and CD8+ T cell subsets were activated in the early stages of sepsis." (PMID 33717146, 2021). "Twenty-four hours after sepsis, there was a significant increase in the frequency of CD69+ CD43+ cells within the CD4+CD44hi subset in water sepsis but not alcohol sepsis." (PMID 27861506, 2016). "Taken together, these data suggest that the reduced CD43 and CD69 expression observed on CD4+ and CD8+ T cells in ethanol-fed animals in the setting of sepsis may be responsible for the dysregulated cytokine response." (PMID 27861506, 2016). "At 24h after sepsis both water and alcohol fed animals significantly increased CD69 expression without a difference between water and alcohol sepsis groups." (PMID 27861506, 2016). "Within 24h, there was a significant increase in the frequency of CD69+CD43+ cells within the CD44lo CD4+ T cell population in water sepsis, while the increase in alcohol sepsis failed to reach significance." (PMID 27861506, 2016). "High levels of CD69 are found in inflammatory infiltrates in vitro, as well as on T cells of critically ill patients with sepsis relative to non-septic controls." (PMID 27861506, 2016). "TCR driven up-regulation of the early activation marker CD69 was virtually indistinguishable among all experimental SIRS/sepsis models and mock treated animals." (PMID 25541945, 2014). "In addition, Tregs strongly upregulated the markers CTLA-4, CD69 and CD25, indicating that they were activated within hours after sepsis induction." (PMID 23724126, 2013). "However, cytokines alone were able to upregulate the expression of CD69 in NK cells from SIRS and sepsis patients." (PMID 23098236, 2012). "• CD69 expression is enhanced on NK cells from SIRS and sepsis patients but may still be futher increased by the addition of IL-15 plus IL18." (PMID 23098236, 2012). "The change in receptor expression pattern that we observed over the course of sepsis, increased TIM-3, LAG-3 and CD69 with decreased IL-7R expression, is consistent with the phenotype of immune cell exhaustion, although the functional impairment was not as severe." (PMID 22742734, 2012). "Decreased expression of CD69, CD36 (DE 1.78 and −5.53 respectively at 18 h) and MHC II genes (H2-OB) in peritoneal cell profiles is consistent with the blood profiles of sepsis patients at late stages of sepsis." (PMID 23009705, 2012). "Thus, the low level CD3+CD4+CD69+T/CD3+CD8+CD69+T ratio in G- sepsis may display an adaptive immune state of excessive CD8+T activation and early occurrence of CD4+T suppression resulting from G- sepsis and correlate with the poor prognosis of G- sepsis." (PMID 36703970, 2022). "Thus, CXCR4 and CD69 might contribute to the selective recruitment and retention of CD8+ TN, TCM, and TVM cells in the BM during sepsis, a hypothesis that remains to be evaluated further." (PMID 36148245, 2022). "CLP induced the expansion of the TN, TCM, and TVM subpopulations and an increased expression of CD69 on TN and TVM cells in the BM of TLR2−/− mice in a similar pattern as observed for WT mice, which argues against a role of TLR2 in the activation of CD8 T cells during sepsis." (PMID 36148245, 2022). "The ratio of CD3+CD4+CD69+T/CD3+CD8+CD69+T (odds ratio (OR): 0.078(0.012,0.506), P = 0.008), PCT>0.53 ng/ml (OR: 9.31(1.36,63.58), P = 0.023), and CO2CP<26.5 mmol/l (OR: 10.99(1.29, 93.36), P = 0.028) were predictive of G- sepsis (versus G+ sepsis), and the area under the curve (AUC) was 0.947." (PMID 36703970, 2022).
Sepsis (continued). "In addition to the increased CD69 expression in the sham groups, the alcohol fed subgroup failed to return to baseline CD69 expression by 72h following sepsis." (PMID 27861506, 2016). "In the present study, we find that CD69 expression correlates both with cytokines stimulating MAIT cell activation and with cytokines produced by MAIT cells, such as IFNγ and TNF, which may indicate that MAIT cells contribute to the pro‐inflammatory cytokine response in sepsis." (PMID 40041474, 2025). "CD69 is not expressed on NK cells from healthy controls and is only expressed on 25 to 30% of NK cells from SIRS and sepsis patients." (PMID 23098236, 2012). "Indeed, flow cytometry indicated higher relative abundance of PD-1+CD4+ Tm cells and CD69+CD4+ Tm cells in patients with heatstroke than in healthy control and patients with cardiopulmonary bypass, but not in patients with sepsis." (PMID 40084252, 2025). "However, acid-base variables did not correlate with CD3+CD69+T subsets in sepsis, indicating acid-base changes didn’t affect CD3+CD69+T subsets ratios." (PMID 36703970, 2022). "Therefore, we supposed that it was sepsis, but not sepsis-induced acid-base alterations, triggered the peripheral CD3+CD69+T subsets changes." (PMID 36703970, 2022). "We found that patients with sepsis did have a higher expression of CD69 on CD4+ T cells at the onset of sepsis, as well as a higher circulating percentage of CD69 expressing CD4+ T cells and this did not significantly change over the course of the acute illness (data not shown)." (PMID 22742734, 2012).
malaria (22 papers, 2009 to 2025). Malaria is a serious and sometimes fatal disease caused by a parasite that commonly infects a certain type of mosquito which feeds on humans. "The number of CD8+CD69+KLRGlow Trm cells have been shown to be associated with malaria liver-stage protection induced by prime-and-trap strategy." (PMID 37056783, 2023). "All forms of malaria were associated with increased numbers of lymphocytes expressing the acute activation marker CD69." (PMID 26581890, 2015). "Our gp96-Ig approach induced an exclusive population of CD8+CD69+KLRG1low liver Trm cells in mice, thus indicating potential implications of gp96-Ig-vaccination in protection against malaria liver-stage infections." (PMID 37056783, 2023). "Patients who died of non-malaria related complications had higher percentages of CD69+ and CD45RO+ cells in their lymph node sections compared to the percentage of these cells in tissue sections from CM and SMA patients." (PMID 36014972, 2022). "This too is consistent with the results of our previous work, in which severe malaria cases were characterized by highly activated T cells in periphery as shown by a high expression of the activation marker CD69." (PMID 36014972, 2022). "In mice suffering from malaria, with the activation of splenic T cells an increase of 3–4 times of the expression of the CD69 marker, captopril provides an immunomodulating effect, restoring the values to control levels." (PMID 34768805, 2021). "Expression of the activation markers CD69 and HLA-DR on Vγ9Vδ2 γδ T cells was higher in malaria cases than in controls (HCs vs UM or CM, p < 0.0001) but was similar between UM and CM." (PMID 31600250, 2019). "Compared to HCs, expression of both CD69 and HLA-DR on Vγ9Vδ2 γδ T cells was higher in malaria cases during acute disease." (PMID 31600250, 2019). "Children with asymptomatic malaria had significantly lower levels of CD69+ expression on CD4+ T cells compared to children with symptomatic disease (P = 0.0016) but had comparable levels with the controls (P > 0.05)." (PMID 30005684, 2018). "The analysis of activated T-cells demonstrated that both malaria groups presented significantly lower counts of CD4+CD69+ and CD8+CD69+ as compared to endemic controls." (PMID 27581163, 2016). "Lymphocyte activation demonstrated by expression of CD69 is characteristic of all three clinical forms of malaria." (PMID 26581890, 2015). "Median percentages of activated CD69+ NK (73%) and γδ T (60%) cells were higher in cerebral malaria than in other malaria types." (PMID 26581890, 2015). "If this occurs in malaria, the reduction in lymphocyte surface CD69 expression in convalescence would enable the rapid restoration of circulating lymphocyte levels observed posttherapy." (PMID 26581890, 2015). "As T cell-mediated immune responses are indispensable for protection against malaria, we first examined the activation of T cells by determining expression of CD69, an early activation marker." (PMID 23527234, 2013). "With regard to malaria, in vitro experiments have shown that CD69 is universally up-regulated on NK cells in response to live intact P. falciparum-infected erythrocytes." (PMID 21625619, 2011). "Consistent with other malaria vaccination studies in rodents, in our model CD69+/CXCR6hi/CSP-tet+ defined Trm cells may be especially critical for protection." (PMID 37609210, 2023). "The predominance of CD69+ cells in the spleen of CM patients is consistent with the results of the Vietnamese study, where the expression of the activation marker HLA-DR on sinusoidal lining cells was increased in the red pulp in fatal malaria cases." (PMID 36014972, 2022). "Interestingly, we also found a lower expression of CD69, a marker of recent activation, on T cells, in the children group with complicated malaria." (PMID 29555909, 2018). "In addition, children with symptomatic malaria had a higher level of the CD4+CD69+ T cells than the controls (P = 0.0068)." (PMID 30005684, 2018).
malaria (continued). "However, malaria patients had higher percentages of early and late activated T cells than AC (CD69, P ≤ .0001; HLA-DR, P ≤ .0003)." (PMID 22853732, 2012). "Given the importance of TRM cells in inducing protection in murine models against virus, bacterial and liver-stage malaria infections, a better understanding of function and longevity of liver sporozoite-specific CD69+ TRM cells could better guide malaria vaccine development." (PMID 28182750, 2017). "Because the time between infection and hospital admission - and hence duration of the ongoing infection - may vary across malaria patients, their T cell activation status was assessed using early and late T cell activation markers, namely CD69 and HLA-DR, respectively." (PMID 22853732, 2012). "This work points to the potential for using CD69+ TRM-like cells in the periphery to estimate liver CD69+ TRM cells, and vaccine-induced protection from malaria." (PMID 35197971, 2022). "In particular, patients with recurrent malaria presented significant reduction of CD4+, CD8+ T-cells and activated T-cells (CD69-expressing CD4+and CD8+ T-cells)." (PMID 27581163, 2016). "Moreover, patients with recurrent malaria displayed decreased absolute counts and percentage of CD4+CD69+ and CD8+CD69+ as compared to primary malaria." (PMID 27581163, 2016). "To investigate whether anti-IP-10 treatment had an effect on T cell activation during malaria, we first examined the percentage of activated CD4+ and CD8+ T cells expressing CD69 and CD25 in anti-IP-10 and isotype-control-treated mice after P. berghei ANKA infection." (PMID 19343215, 2009). "Only children with uncomplicated malaria, but not children with complicated malaria, showed an increase in the proportion of CD39+, CD69+, and GrzB+ CD4+ T cells." (PMID 29555909, 2018). "Although the heterogeneity in the response of CD40L and IFNγ suggests that our tested malaria antigens did not induce significant differences in the expression of these markers in all our participants, our panel did not include other activated induced markers, such as OX40, 4-1BB, and CD69." (PMID 40402846, 2025).